ENO2 (enolase 2)
Description:
Enolase that catalyzes the conversion of 2-phosphoglycerate to phosphoenolpyruvate in glycolysis and the reverse reaction in gluconeogenesis (By similarity). Has neurotrophic and neuroprotective properties on a broad spectrum of central nervous system (CNS) neurons. Binds, in a calcium-dependent manner, to cultured neocortical neurons and promotes cell survival (By similarity).
Synonyms: NSE; HEL-S-279
Tractability: Small molecule: a structure with a bound ligand is known; it has a binding pocket of medium quality. Antibody: its Gene Ontology location is reachable by antibodies, with high confidence; UniProt places it where antibodies can reach, with medium confidence; the Human Protein Atlas places it where antibodies can reach. PROTAC: UniProt records ubiquitination sites on it; ubiquitination databases record sites on it; its protein half-life has been measured.
Gene: Protein-coding gene on chromosome 12 (6,913,745 to 6,923,707, forward strand). Ensembl gene ENSG00000111674.
Subcellular location: Cytoplasm; Cell membrane
Subcellular location (Human Protein Atlas): Cytosol; Plasma membrane
Pathways (Reactome):
Metabolism: Gluconeogenesis; Glycolysis
Gene Ontology:
Molecular function: protein binding; phosphopyruvate hydratase activity; enzyme binding; identical protein binding; magnesium ion binding; protein-containing complex binding
Biological process: canonical glycolysis; gluconeogenesis; glycolytic process; response to estradiol; response to xenobiotic stimulus
Cellular component: cytosol; extracellular exosome; extracellular region; membrane; plasma membrane; phosphopyruvate hydratase complex; cell cortex; cell surface; cytoplasm; growth cone; membrane raft; neuronal cell body; perikaryon; photoreceptor inner segment; synaptic membrane
Genetic constraint (gnomAD): Loss-of-function variants: 19 observed, 51.44 expected, observed/expected ratio (o/e) 0.37, 90% interval 0.26 to 0.54. The upper end of that interval is the gene's LOEUF score, 0.54, which puts it in group 2 of 6, group 1 being the genes least tolerant of losing a copy. Missense variants: 416 observed, 582.97 expected, observed/expected ratio (o/e) 0.71, 90% interval 0.66 to 0.77. Synonymous variants: 198 observed, 226.19 expected, observed/expected ratio (o/e) 0.88, 90% interval 0.78 to 0.99.
Homologues: Orthologues: chimpanzee ENO2 (100% identical), macaque ENO2 (99% identical), dog ENO2 (99% identical), rabbit ENO2 (99% identical), guinea pig ENO2 (99% identical), mouse Eno2 (99% identical), pig ENO2 (99% identical), rat Eno2 (98% identical), zebrafish eno2 (84% identical), Caenorhabditis elegans enol-1 (74% identical), Drosophila melanogaster Eno (72% identical). Paralogues in human: ENO1 (83% identical), ENO3 (83% identical), ENO4 (26% identical).
Diseases named in the same sentence as ENO2 in open-access papers:
ENO2 is named in the same sentence as 460 diseases in open-access papers, as found by Europe PMC text mining. Sharing a sentence is not in itself a finding about the gene and the disease. The quoted sentences say what the papers report.
lung cancer (257 papers, 1986 to 2026). A malignant neoplasm involving the lung. "Overexpression of ENO2 was also associated with a worse prognosis for lung cancer patients." (PMID 38967113, 2024). "In addition, expression of ENO2 was reportedly linked to prognosis for several cancers, including colorectal cancer, lung cancer, and pancreatic cancer." (PMID 33324198, 2020). "Six genes (PGK1, ENO2, GPI, PEKP, ALDOA, and ANGPTL4) were reported as hypoxia-related genes in lung cancer." (PMID 38248716, 2023). "To further evaluate the association of LMO1 expression with neuroendocrine differentiation in lung cancer cells, we examined the correlation between LMO1 mRNA levels and mRNA levels of neuroendocrine markers, including chromogranin A (CHGA), synaptophysin (SYP) and neuron-specific enolase-2 (ENO2)." (PMID 30038707, 2018). "In order to directly identify candidate mediators that are relevant to both lung cancer tumorigenesis and patient survival, we began with genes displaying significant correlation with mRNA levels of LMO1 and neuroendocrine markers CHGA, SYP and ENO2 levels in the MDACC dataset." (PMID 30038707, 2018). "Besides, we calculated the 5hmC level of clinically known but nonspecific markers for lung cancer in control and tumor groups, including CEA, CA125 (MUC16), NSE (ENO2), and CYFRA21-1 (KRT19)." (PMID 30010036, 2018).
neuroendocrine tumors (110 papers, 1986 to 2025). "Enolase 2 (ENO2), a crucial glycolytic enzyme in cancer metabolism, is associated with the metastasis of multiple cancers and is also used as a marker for neuroendocrine tumours." (PMID 39061144, 2024). "Eno2 is a general tumor marker for neuroendocrine tumors, and is used to aid in cancer diagnosis, prognosis, and characterization." (PMID 39861068, 2024). "Among these, known biomarkers for MB (FSTL5), and other tumor types such as neuroendocrine tumors (ENO2, FMOD, ART3, COL6A3) and PIP, were found to be significantly up-regulated (dark green)." (PMID 32466393, 2020). "Furthermore, genes encoding canonical markers of neuroendocrine tumors—including CHGA (chromogranin A), SYP (synaptophysin), NCAM1 (CD56), and ENO2 (neuron-specific enolase)—were all differentially higher in s3 tumors." (PMID 36731467, 2023). "We next focused on enolase 2 (ENO2), a glycolysis enzyme upregulated in a variety of neuroendocrine tumors, including kidney AML 30–32." (PMID 34764250, 2021). "Eight genes (CHGA, CPE, ENO2, INSM1, PTPRN2, SERPINA10, and SLC18A1/2) that have been previously identified as markers of neuroendocrine tumors were confirmed in this study to be altered." (PMID 21853033, 2011).
small cell lung carcinoma (107 papers, 1985 to 2025). Small cell lung cancer (SCLC) is a highly aggressive malignant neoplasm, accounting for 10-15% of lung cancer cases, characterized byrapid growth, and early metastasis. "Enolase 2 (ENO2) is another important glycolytic enzyme that is overexpressed in prostate cancer, small-cell lung cancer, metastatic neuroblastoma, and leukemia." (PMID 37795435, 2023).
neuroblastoma (72 papers, 1987 to 2026). Neuroblastoma (NB) is the most common solid, extracranial childhood tumor. "We further analysed the expression of differentiation-related genes (SYP, NEFL, ENO2, MAPT) in high-risk neuroblastoma patients and correlated them to HIF1A expression." (PMID 34557995, 2022). "Since HIF1α is a transcription factor, we next asked if peroxides play indispensable role in HIF-dependent transcription by examining Eno2 and Bnip3 mRNA expression levels, which are two established HIF1α target genes, in neuroblastoma SH-SY5Y cells." (PMID 34596045, 2021). "Other studies showed downregulation of ENO2 in a neuroblastoma cell line with silencing of HIF-1A." (PMID 39567394, 2024). "Immunohistochemistry of neuroblastoma tumours demonstrates that (i) synaptophysin is constitutively expressed by neuroblastoma tumoural cells, (ii) NEFL gene mutation is common yet inefficient in neuroblastoma tumours, and (iii) neuron-specific enolase (ENO2) is a non-favourable marker." (PMID 34557995, 2022).
prostate carcinoma (42 papers, 1994 to 2025). A carcinoma that arises from epithelial cells of the prostate gland. "NEPC does not secrete prostate-specific antigen (PSA) and is a highly aggressive subtype of prostate cancer characterized by the following features: unresponsiveness to hormone therapy and expression of neuroendocrine markers such as enolase 2 (NSE)." (PMID 33029516, 2020). "ENO2 (neuron-specific enolase, NSE) is a marker that is characteristically expressed in neuroendocrine prostate cancers and is used in clinical settings to determine prostate cancer progression." (PMID 27015368, 2016). "The genotypic characteristics of this prostate cancer variant are highly variable and also show the expression of genes that are used as markers for neuroendocrine (NE) differentiation, e.g., synaptophysin (SYP), chromogranin A (CgA), and enolase 2 (ENO2)." (PMID 35741197, 2022). "We transiently expressed ID2 in a panel of prostate cancer cell lines; Western blot analysis showed decreased expression of AR and PSA in LNCAP cells, while the expression of NE markers such as CHGA, ENO2, and SYP was elevated in both LNCAP and PC3 cells." (PMID 38254880, 2024). "Overexpression of NK1R in epithelial prostate cancer cells was able to induce a shift of lineage plasticity, leading to the reduction of AR and PSA levels, the gain of the expression of CgA, ENO2, AURKA, N-Myc, MYT1, and SRRM4." (PMID 37385990, 2023). "Indeed, treating several prostate cancer cell lines with GSK126, an inhibitor of EZH2, resulted in REST induction and reduced NE marker ENO2 expression." (PMID 38777812, 2024). "The lack of expression of the prostate-specific genes (AR, NKX3.1, and PSA) at the protein level prompted the investigation of a possible NE prostate cancer phenotype, which was confirmed at the RNA-seq level when 2 NE specific marker (SYP and ENO2) were expressed at RNA-seq." (PMID 36643868, 2022). "Prostate cancer with neuroendocrine differentiation is typically defined by the heterogeneous histological expression of several NE markers in at least 5% of epithelial cells, including chromogranin A (CHGA), synaptophysin (SYP), neural cell adhesion molecule 1 (NCAM1), and enolase 2 (ENO2)." (PMID 36033483, 2022). "Similarly, primary marrow fat cells and adipocyte cell lines trigger metabolic reprogramming of bone metastatic prostate cancer cells by enhancing the expression of PDK1, enolase 2 (ENO2), LDHA as well as HK2 and GLUT1, already mentioned as Notch downstream effectors in breast cancer cells." (PMID 30873026, 2019).
non-small cell lung carcinoma (32 papers, 1995 to 2025). A group of at least three distinct histological types of lung cancer, including non-small cell squamous cell carcinoma, adenocarcinoma, and large cell carcinoma. "Up-regulated expression of the ENO2 gene has also been observed in non-small cell lung carcinomas (NSCLCs)." (PMID 33226369, 2020). "Other enzymes, such as PGI, PGK-1 and ENO-2, were found to be downregulated in an epidermal growth factor receptor (EGFR)-mutant non-small-cell lung cancer (NSCLC) with advanced resistance to EGFR tyrosine kinase inhibitors (TKIs), such as erlotinib." (PMID 39904372, 2025).
melanoma (28 papers, 1998 to 2025). A malignant, usually aggressive tumor composed of atypical, neoplastic melanocytes. "Interestingly, Enolase 2 and CapG are used as tumour markers in the diagnosis and prognosis of several cancer types, and both proteins have been associated with cell proliferation, invasion, migration, and metastatic capacity in several types of cancer, including melanoma." (PMID 34885166, 2021). "This may be compensatory for the downregulation of its counterpart ENO1 and ENO2, suggesting that the role of enolases needs to be explored in melanoma." (PMID 33937086, 2021). "Our results revealed for the first time that silencing the OPN gene influences proliferation and invasion of melanoma cells by effecting EGFR, tenascin C, survivin, galectin-3 and enolase 2 expression." (PMID 34257527, 2021).
breast carcinoma (23 papers, 2011 to 2025). "Gene expression analysis has shown ENO2 mRNA to be elevated in breast cancer lymph node metastases compared to primary breast tumors and ENO2 mRNA to be upregulated in the estrogen receptor positive subset of 36 invasive ductal breast carcinomas." (PMID 22098917, 2011). "Although there is a paucity of data on the relevance of ENO2 to the progression of breast and prostate cancers, ENO2 mRNA was found to be elevated in breast cancer lymph node metastases compared to primary breast tumors, which may suggest its role in breast cancer progression." (PMID 40214422, 2025). "To clarify the role of compression-induced upregulation of ENO2, HK2, or PFKFB3 genes in breast cancer progression, we investigated genetic alteration of the genes." (PMID 31428701, 2019). "Neuron specific enolase (ENO2, γ-enolase) has been used as a biomarker to help identify neuroendocrine differentiation in breast cancer." (PMID 22098917, 2011). "In this regard, in our study, we demonstrate that the combined knockdown of ALDOC and ENO2 significantly reduced lactate production and consequently attenuated the sphere-forming ability of both LUAD and breast cancer cell lines both in nutrient-rich and nutrient-restricted conditions." (PMID 36945054, 2023). "Among the compression-upregulated metabolic genes, the expression of ENO2 gene was significantly and positively correlated with COL3A1 and HAS1 genes, whereas PFKFB3 genes were significantly and positively correlated with that of COL1A1, HAS2, and HAS3 genes in breast cancer patient tissues." (PMID 31428701, 2019).
colorectal cancer (20 papers, 2008 to 2025). A primary or metastatic malignant neoplasm that affects the colon or rectum. "In light of previous scientific inquiries, it’s compelling to mention that many of the genes within this list of 10, specifically CAV1, DAPK1, GPX3, IGFBP6, TIMP1, GADD45B and ENO2 have been found associated intimately with colorectal cancer, as documented by several research studies." (PMID 38501104, 2024). "Through knocking down and overexpressing ENO2, another study demonstrated ENO2′s role in driving the metastasis of colorectal cancer (CRC) cells by activating the YAP1-induced EMT process but was independent of glycolysis regulation." (PMID 39061144, 2024). "ENO2 has been upregulated in various tumor types, including head and neck cancer, colorectal cancer, pancreatic cancer, and bladder cancer, and has been associated with more aggressive phenotypes." (PMID 37760940, 2023). "Along with other glycolytic genes, ENO2 was previously found to be overexpressed in colorectal cancer and other cancer types." (PMID 30967137, 2019). "For example, ENO2 was involved in the oncogenic process of BRAF V600E colorectal cancer by regulating the MAPK/ERK signaling pathway and may be a novel therapeutic target for BRAF V600E mutant colorectal cancer." (PMID 38724951, 2024). "Moreover, ENO2 is a glycolysis-related gene that has been described to play an important role in tumorogenesis of colorectal cancers." (PMID 18694510, 2008). "We examined the expression of has_circ_0074854, miR-2110, ENO2, and IGF2BP3 in 30 colorectal cancer tissues and investigated their interrelationships." (PMID 37644235, 2023). "Loss of NAT2, a non-essential enzyme involved in drug metabolism, in colorectal cancers emerged as an attractive target conceptually different from synthetic lethality (ENO2, PRMT5, ME3) or targeting genes essential for cell survival (POLR2A, RPA70, or PSMC2)." (PMID 32161261, 2020).
pancreatic cancer (16 papers, 2014 to 2025). "To investigate the possible role of ENO2 in pancreatic cancer progression, we first analyzed ENO2 mRNA levels based on two Gene Expression Omnibus (GEO) datasets (GSE28735 and GSE15471)." (PMID 32398667, 2020). "Overall, ENO2 mRNA was found to be significantly increased in pancreatic cancer tissues compared with normal tissues (P < 0.001)." (PMID 32398667, 2020). "Histone modification is considered an important transcriptional regulatory mechanism and is involved in the progression of multiple tumors, for example, HDAC3-mediated deacetylation leads to ENO2 activation in pancreatic cancer, and the HDAC4-RelB-p52 complex regulates multiple myeloma growth." (PMID 35892859, 2022). "Finally, they created a signature defined by the expression ratio of the glycolytic gene ENO2 (neuron-specific enolase) and several lipid genes, further validated in 200 non-pancreatic cancer cell lines." (PMID 33371431, 2020). "We selected the marker genes (ADM, ERO1A, ENO2, BNIP3, and UPP1) of CAF-C2 to detect their expression in human pancreatic CAF-stellate cell (CAF118), human pancreatic cell (HPC-Y5), and human pancreatic cancer cell line." (PMID 36544710, 2022). "K394 acetylation was further verified by immunoprecipitation (IP) of endogenous ENO2 in HEK293T and pancreatic cancer cells." (PMID 32398667, 2020). "Thus, the overexpression of enolase 2/neuron-specific enolase (ENO2/NSE), an important glycolytic enzyme, has been reported as an EMT inductor in pancreatic cancer cells, thereby promoting metastasis." (PMID 36500393, 2022).
renal cell carcinoma (16 papers, 2007 to 2024). "In a more recent investigation, an MS-based proteomics workflow for identifying differentially abundant proteins in renal cell carcinoma (RCC) demonstrated elevated levels of enolase 2 (ENO2) and thrombospondin-1 (TSP1) in tumor TIF." (PMID 21980378, 2011).
glioma (15 papers, 2008 to 2025). A benign or malignant brain and spinal cord tumor that arises from glial cells (astrocytes, oligodendrocytes, ependymal cells). "We previously demonstrated that glioma cells with ENO1 passenger deletions are selectively susceptible to inhibition of ENO1’s redundant paralog ENO2 through the collateral lethality paradigm." (PMID 34172075, 2021). "DePinho and colleagues found that ENO1 was often deleted in glioblastomas and rendered glioma cells more sensitive to the inhibition of ENO2, herein proposed collateral damage caused by passenger deletions of redundant essential genes as a novel therapeutic strategy." (PMID 35156101, 2021). "For example, glioma cells carrying a large deletion including the ENO1 gene cannot survive when the paralogue ENO2 was inhibited." (PMID 37984988, 2024). "Glioma cells treated with gp120 (100 ng/mL for 7–10 days) showed higher proliferation rates and upregulation in the expression of enolase 2, hexokinase and glyceraldehyde-3-phosphate dehydrogenase when compared to untreated cells." (PMID 30200472, 2018). "We observed an upregulation of the key glycolytic enzymes HXK, GAPDH and ENO2 in glioma cells treated with gp120." (PMID 30200472, 2018). "Then, they used gliomas with deletion of ENO1, but sensible to enolase inhibitors because of the expression of ENO2." (PMID 38139462, 2023). "A significant increase in protein expression was observed for hexokinase (HXK), ENO2 and GAPDH in all the glioma cell lines tested." (PMID 30200472, 2018). "We selected seven glycolytic genes (HK2, PFKP, ALDOA, PGAM1, ENO1, ENO2 and PDK1) and confirmed their strong up-regulation under hypoxia by QPCR in seven GBM cell lines (five patient derived glioma stem-like cells and two adherent GBM cell lines)." (PMID 25932951, 2015). "A preliminary report showed that the serum levels of a tissue-specific isoform known as neuron-specific enolase (NSE), also known as ENO2, have not been correlated to a worse prognostic value in glioma patients yet." (PMID 38139462, 2023). "Using this concept of collateral lethality, we validated that in a subset of gliomas with 1p36 deletions, passenger deletion of the glycolytic gene ENO1 selectively renders cancer cells sensitive to inhibition of the redundant isoform ENO2." (PMID 34172075, 2021).